CD4 (CD4 molecule)
Diseases named in the same sentence as CD4 in open-access papers (continued):
Sharing a sentence is not in itself a finding about the gene and the disease.
lupus (continued). "Consistent with the higher number of CD4+ T cells in lupus mice, the number of proliferating cells was higher for all three subsets in TC mice." (PMID 30348969, 2018). "Nevertheless, CD4+ T cells seem to be of greatest importance, as both SLE patients and lupus-prone mice show a characteristic activation of these cells, and inhibitors normalizing CD4+ T-cell reactions exhibit therapeutic effects." (PMID 30563559, 2018). "A potential effect of metformin was supported by the fact that as for CD4+ T cells from lupus prone mice, both glycolysis and respiration were elevated in KBN CD4+ T cells." (PMID 30233578, 2018). "CD4+ T cells are of great importance in the pathogenesis of systemic lupus erythematosus (SLE), as an imbalance between CD4+ regulatory T cells (Tregs) and CD4+ responder T cells (Tresps) causes flares of active disease in SLE patients." (PMID 30563559, 2018). "To further confirm the inhibitory effect of HCQ on NFATc2 nuclear translocation, we performed immunocytochemistry analysis in purified lupus CD4+ T cells." (PMID 28793932, 2017). "In particular, the induction of DR6+ CD4+ T cells correlated with age- and genetic background-dependent disease progression and prognosis in lupus-prone mice." (PMID 28045014, 2017). "Not only miR-21 is induced by T cell activation and enhances the T cell immune response but also miR-21 has been shown to induce proliferation of CD4+ T cells in murine models of systemic lupus erythematosus (SLE) and in patients with SLE." (PMID 28360962, 2017). "All these results indicated that the cytotoxicity of NKG2D+CD4+ T cells on NKG2DL+ Treg cells contributed to the remarkable decrease in Treg cells frequency in lupus." (PMID 28455530, 2017). "We found that the ratio of peripheral CD8+ to CD4+ T cells increased in lupus-prone and pristane-treated mice." (PMID 29163765, 2017). "Studies have investigated the significant role of histone modifications in regulating CD70 expression through affecting the posttranslational marks within the TNFSF7 promoter region in lupus CD4+ T cells." (PMID 28785369, 2017). "The relationship between globally reduced DNA methylation in lupus is further confirmed when a lupus-like syndrome is induced by treating CD4+ T cells with DNA methylation inhibitors." (PMID 28785369, 2017). "This ability for IFN-γ secretion by CD4+CD25−FoxP3+ cells was previously shown by Yang in the context of lupus patients." (PMID 28536578, 2017). "We also checked frequency of PD-1 on different CD4+ T-cell subsets including Teff, Tregs, and Tnaïve/mem cells to assess for differences between active and inactive lupus patients as PD-1 has been shown to play a role in T-cell exhaustion." (PMID 28555177, 2017). "This includes systemic lupus erythematosus where dual treatment of 2-DG and metformin normalizes CD4+ T-cell metabolism, and cancer where microRNA is being used to target glycolysis." (PMID 29170670, 2017). "P140 corresponds to a portion of the spliceosomal U1-70K snRNP protein, recognized by lupus CD4+ T cells." (PMID 28934328, 2017). "Aberrant CD11a overexpression in CD4+ T cells induces T cell auto-reactivity, which is an important factor for systemic lupus erythematosus (SLE) pathogenesis." (PMID 28430662, 2017). "Beyond that, regulatory factor X1 (RFX1) and the nuclear factor interleukin-3-regulated protein (NFIL3, also known as E4BP4) are also reported in our previous study in human lupus CD4+ T cells." (PMID 28785369, 2017). "Next, using purified CD4+ T cells from lupus patients, we also found that HCQ pretreatment significantly decreased NFATc1 expression in activated CD4+ T cells." (PMID 28793932, 2017). "In this regard, levels of CD4+NKG2D+ cells have been found to correlate inversely with disease activity in patients with systemic lupus erythematosus, although their suppressive function is apparently preserved." (PMID 29038617, 2017).
lupus (continued). "The effect of 6H3 in the BMDCs-ALD-DNA induced lupus model was diminished by CD4+ T cell depletion, in accordance with B7-H4-KO-BMDCs-ALD-DNA-induced sever lupus mice syndrome dependent on CD4+ T cells." (PMID 29321778, 2017). "CD4+ T-cell counts were also decreased in eight patients with systemic lupus erythematosus who also suffered from cryptococcal meningitis (mean ± SD, 113.2 ± 59.2/μL)." (PMID 28035481, 2017). "miR-146a has been found to be downregulated in CD4+ T cells from lupus patients as compared to healthy controls, and it was conversely linked to disease prognosis." (PMID 28785369, 2017). "Recently, a population of IL-10-producing thymic B cells of the CD19+CD5+CD1dhigh phenotype was detected and characterized by the activity to reduce the number of SP CD4+CD8− and CD8+CD4− thymocytes and suppress the autoimmune response in lupus-like mice." (PMID 28477096, 2017). "CD4+ T cells from patients with active lupus were also found to overexpress perforin, CD70, CD40L, and KIR due to demethylation in the respective promoters." (PMID 27199979, 2016). "Demethylated, autoreactive CD4+ T cells overstimulate antibody production by B cells and kill macrophages, thus releasing apoptotic nuclear material that stimulates lupus-like autoantibodies." (PMID 27199979, 2016). "Studies of systemic lupus erythematosus (SLE) identified hundreds of 5mC sites in CD4+ T cells associated with the disease phenotype with median p values of ~10−7, while median p values of ~10−3 were found associated with SLE when DNA from the whole blood leukocyte fraction was examined." (PMID 27462403, 2016). "ICOS expression has been found to be enhanced in CD4+ T cells from lupus patients compared to healthy donors and ICOS levels were higher in patients with nephritis than in those without nephritis." (PMID 27635407, 2016). "Increased levels of frequencies of IL-22 + CD4 + T cells have been observed in patients with psoriasis, active systemic lupus erythematosus (SLE) and rheumatic arthritis (RA)." (PMID 27338754, 2016). "MBD4 is involved in the apoptosis signaling pathway and found to be overexpressed by lupus CD4+ T cells." (PMID 28035990, 2016). "Increased miR-21 expression in CD4+ T cells from both lupus patients and lupus-prone MRL/lpr mice promoted cell hypomethylation by repressing RAS guanyl-releasing protein 1 (RASGRP1) expression." (PMID 27271606, 2016). "We found that PP5 mRNA levels are significantly higher in CD4+CD28+ T cells from lupus patients relative to controls." (PMID 28239687, 2016). "CD4+ T cell profile of SLE patients with active disease are characterized by global H3 and H4 hypoacetylation in active lupus CD4+ T cells and disease activity correlates negatively with H3 acetylation as measured by SLEDAI." (PMID 27669210, 2016). "The PP5 over-expression is consistent with the decreased Dnmt1 levels and increased KIR, perforin, CD40L, CD70, and CD11a expression seen in CD4+CD28+ T cells from lupus patients." (PMID 28239687, 2016). "The levels of GADD45a are inversely proportional to DNA methylation levels in human lupus CD4+ T cells." (PMID 27199979, 2016). "OX40 expression by lupus peripheral blood cells was found to be predominantly restricted to memory CD45RO+ CD4+ T cells and its levels correlated with disease activity." (PMID 27635407, 2016). "Surprisingly, other researchers have reported increased percentages of CD4+ FOXP3+ in lupus and found that this result correlated with disease activity." (PMID 27887663, 2016). "It is considered that aberrant histone modifications within the TNFSF7 promoter accompanied with other mechanisms lead the way to the development of lupus through elevating CD70 level in CD4+ T cells." (PMID 27669210, 2016). "A large scale genomewide DNA methylation study in isolated CD4+ T cells from lupus patients found 236 hypomethylated CG sites." (PMID 27594771, 2016).
lupus (continued). "ERK pathway signaling in CD4+ lupus T cells is defective, due at least in part to impaired PKCδ activation, caused by oxidative damage." (PMID 28239687, 2016). "We therefore compared PP5 mRNA levels in CD4+CD28+ T cells freshly isolated from lupus patients with varying levels of disease activity to CD4+CD28+ T cells isolated from age and gender matched healthy volunteers." (PMID 28239687, 2016). "In this study, we found that the global DNA methylation levels are decreased not only in lupus CD4+ T cells, but also in purified lupus CD19+ B cells, as well as in splenic CD4-CD19- cells." (PMID 27070142, 2016). "FOXP3-expressing CD8+ T cells proved vital for CD4+CD25+ Tregs induced by a tolerogenic peptide to suppress murine lupus." (PMID 27887663, 2016). "It is also possible that the steroid effect observed on Tregs is disease-dependent, as CD4+ T cell homeostasis is markedly perturbed in Lupus patients." (PMID 26629828, 2015). "The level of miR-148a is remarkably increased in human lupus CD4+ T cells compared to healthy controls." (PMID 26473848, 2015). "To investigate inherent epigenetic differences in T cells between ethnicities, we characterized genome-wide DNA methylation patterns in naïve CD4+ T cells in healthy African-Americans and European-Americans, and then confirmed our findings in lupus patients." (PMID 26609326, 2015). "Activated CD4+ T cells accumulate in lupus-prone mice and promote disease development, in part, by providing cognate help for autoreactive B cells." (PMID 25867237, 2015). "Increased proportions of CD4+CD25−FoxP3+Treg are observed in particular in patients with systemic lupus erythematosus (SLE), especially in patients with lupus nephritis, a major cause of mortality and morbidity in SLE." (PMID 26525134, 2015). "Next to this, it is the promotion of DNA demethylation in lupus CD4+ T cells that lead to the increased expression of gadd45A, showing that the environment and epigenetics work closely together to determine the expression of disease in an individual." (PMID 25566322, 2014). "We also show that neutrophils from BCMA deficient lupus-prone mice induce CD4+ T cell proliferation and IFNγ production in a BAFF-dependent manner more potently compared to neutrophils from BCMA sufficient lupus-prone mice." (PMID 25010693, 2014). "An increased Mer and Tyro3 expression on CD4+ cells was noted in lupus patients compared with normal control subjects." (PMID 24650765, 2014). "To evaluate the relative contribution of BAFF generated by neutrophils from lupus-prone mice to mediate cytokine production in CD4+ T cells of WT mice, we utilized a BR3 blocking mAb." (PMID 25010693, 2014). "It is also of interest that diabetes can be adoptively transferred by either CD4 or CD8 effector cell while murine lupus relies most heavily on the CD4 compartment." (PMID 25171173, 2014). "Overexpression of several miRNAs, such as miR-21, -148a, -126, and -29b, is reported to affect DNA methylation machinery of lupus CD4+ T cells by targeting DNMT1." (PMID 24991086, 2014). "Foxp3-expressing CD8+ T proved vital for CD4+CD25+ Treg cells induced by a tolerogenic peptide to suppress murine lupus." (PMID 24475019, 2014). "Surprisingly, a small but significant increase in Tyro3 expression was present on CD4+ T cells in lupus patients." (PMID 24650765, 2014). "CXCR3+CD4+ T cells are significantly elevated in the urine of lupus patients with active nephritis flares and are a useful biomarker for renal disease activity." (PMID 24945254, 2014). "ERK activity has been found to be suppressed in lupus CD4+ T-cells, and recent studies have demonstrated that the lupus ERK signaling defect is indeed related to impaired protein kinase C (PKC) phosphorylation." (PMID 25216337, 2014). "During this study we found that lupus-prone mice trended towards increased expression of PD-1 on CD4+ T cells from infected mice as compared to T cells from infected wild type mice (data not shown)." (PMID 25360768, 2014).
lupus (continued). "BR3 expression levels on CD4+ T cells from lupus-prone mice were slightly higher, as measured by mean fluorescence intensity (MFI) values but were not significant." (PMID 25010693, 2014). "For example, a marked increase in BEND3+ T cells in CD4+ or CD8+ T cells was observed in some patients with systemic lupus erythematosus (SLE)." (PMID 25400923, 2014). "Freshly isolated CD4+ T lymphocytes from pristane-induced lupus mice were activated with anti-CD3/CD28 antibodies (3 μg/ml) and interleukin-2 (IL-2) (200 U/ml) with or without resveratrol (0, 10, 20, 40, or 80 μM)." (PMID 25501752, 2014). "Transfer of CD4+CD25+ Tregs from syngeneic normal mice into SLE model mice can effectively suppress the progress of lupus autoimmune phenotypes, such as increased level of ds-DNA antibody and lupus nephritis." (PMID 25133199, 2014). "Reduced levels of forkhead box P3 (FoxP3) in CD4+ Tregs in patients with active lupus are generally believed to be the reason why these patients have less Tregs-suppressive activity than their counterparts with inactive disease." (PMID 24864268, 2014). "Long-term depletion of neutrophils using the mAb, 1A8, significantly reduced the frequency of IFNγ-producing CD4+ T cells and the autoimmune phenotype in BCMA-deficient lupus-prone animals." (PMID 25010693, 2014). "CD4+ T cells and B cells are intimately associated with SLE and pristane-induced lupus." (PMID 25501752, 2014). "An interesting study looked at the role of growth arrest and DNA damage-induced 45α gene (GADD45α) in lupus CD4+ T cells." (PMID 25566322, 2014). "A variable expression of regulatory microRNAs in lupus CD4+ T cells due to epigenetics has been described." (PMID 24991086, 2014). "Data from 20 lupus patients show CD8+CD25+ Treg cells less suppressed CD4+ T cell proliferation in active LN, IVMP increased CD8+CD25+ Treg cells suppression of CD4+ T cells proliferation." (PMID 24475019, 2014). "Taken together, our results suggest that resveratrol has protective properties in a pristane-induced lupus animal model that appear to be attributed to its inhibitory effect on CD4+ T cells and B cells." (PMID 25501752, 2014). "DNA hypomethylation of specific regulatory elements leads to overexpression of perforin in CD4+ T cells, contributing to monocyte killing in systemic lupus erythematosus." (PMID 25414732, 2014). "In our settings, we found that CTX induced a virtually complete inhibition of the proliferation of CD4+ Tcon in lymphoid organs and the peripheral blood of lupus mice." (PMID 23446139, 2013). "Consistent with observations in humans with lupus, CD4+ T cells from MRL/lpr mice had increased measures of mitochondrial potential (DiOC6), intracellular reactive oxygen (DCF-DA), and nitric oxide and peroxynitrite (DAR-4M)." (PMID 23741359, 2013). "Within 3 weeks of transfer, mice develop lupus-like phenotypes including lymphocyte activation and anti-nuclear autoAbs, which are dependent on interactions between donor CD4+ T cells and host autoreactive B cells." (PMID 23566364, 2013). "In vitro treatment of lupus CD4+ T cells with a histone deacetylase inhibitor was demonstrated to overexpress CD70 in these cells by aberrant histone modifications (increase in H3 and H4 acetylation levels) within the TNFSF7 promotor region." (PMID 24000287, 2013). "In systemic lupus erythematosus CD4 positive T cells, downregulation of miR-142-5p/3p correlates with increased methylation of the 3 CpGs directly upstream of pre-mir-142 and an enrichment of H3K27me3." (PMID 24236112, 2013). "The overexpression of miR-148a has also been investigated in CD4+ T cells from patients with lupus as well as lupus-prone mice." (PMID 23983769, 2013). "Although the role of B cells in disease promotion in lupus has been well established, the precise nature of the CD4+ T cells that help autoreactive B cell maturation is less clear." (PMID 24069401, 2013).
lupus (continued). "The estrogen-upregulated miRNA miR-148a was increased in CD4 T cells from human lupus patients and positively correlated with lupus activity." (PMID 24175965, 2013). "PMA-stimulated CD4+ T cells from patients with lupus showed an impaired PKCδ activity state compared with CD4+ T cells from healthy donors." (PMID 22888329, 2012). "In a recent study, miR-21 was found to be up-regulated in B and T cells of B6.Sle123 mice, consistent with findings in another genetic mouse model of lupus as well as in human lupus CD4+ T cells and B cells." (PMID 22230293, 2012). "These investigators were also able to induce the potential alleviation of hypomethylation in CD4+ T cells from patients with lupus by transfection with miR-21 and miR-148a inhibitors." (PMID 21941583, 2012). "The expression of specific genes, such as perforin, is increased in CD4+ lupus cells and this is accompanied by hypomethylation at their promoters." (PMID 22642378, 2012). "Overall, these results suggest that the integration of the TGBβ and RA pathways that are involved in the induction of CD4+ T cell subsets are defective in lupus patients." (PMID 21708033, 2011). "Basic parameters of our lupus cohort confirmed previous findings, such as reduced numbers of CD4+ T cells, skewed memory to naïve CD4+ T cell ratios and a reduced CD25+ Treg compartment in patients with active renal disease." (PMID 21708033, 2011). "Of note, the protective effect of atRA/TGF-β-primed CD4+CD25+ cells on lupus survival was even better." (PMID 21931768, 2011). "We found that PBX1-d was expressed more frequently in the CD4+ T cells from lupus patients than from HCs, and its presence in CD4+ T cells correlated with an increased central memory population." (PMID 21708033, 2011). "The status of CD4+ CD25+ FOXP3+ regulatory T cells (Tregs) in lupus has been examined by numerous studies." (PMID 21708033, 2011). "To validate and compare the therapeutic effects of both CD4+ Treg populations generated as above, we have used a rapid-read lupus model as previously reported." (PMID 21931768, 2011). "Our group previously showed that global H3K9 is globally hypomethylated in active and inactive lupus CD4+ T cells." (PMID 21192791, 2010). "We believe that further studies are warranted to determine the mechanism for increased IL-17 production from CD4+ T cells in human lupus." (PMID 20334681, 2010). "In lupus, CD4+ T cells are critical drivers of the B-cell-dependent autoantibody response through provision of co-stimulatory signals and cytokines." (PMID 20334681, 2010). "We noticed a strong correlation between the frequencies of CD4+IL-17+ T cells and CD4+CCR4+CCR6+ T cells in the peripheral blood of lupus patients." (PMID 20334681, 2010). "CD11a and CD70 are both overexpressed in CD4+ T cells of lupus patients, and the degree of overexpression is directly proportional to disease activity." (PMID 21192791, 2010). "In our study, lupus patients with nephritis had a trend toward an increased frequency of CD4+IL-17+ T cells and CD3+CD4-IL-17+ T cells compared with those without nephritis." (PMID 20334681, 2010). "To determine if adoptive transfer of a mixed population of exogenously expanded CD4+CD25+ Tregs can suppress murine lupus, we transferred cells to a large cohort of 29 week-old B/W mice without clinical disease." (PMID 19551149, 2009). "We previously demonstrated that transfer of expanded CD4+CD25+CD62LHI Tregs slows the development of lupus in (NZBxNZW)F1 (B/W) mice." (PMID 19551149, 2009). "Here we explore the impact of transferring the more comprehensive, but less pure Treg subset defined by CD4+CD25+ expression on development of murine lupus." (PMID 19551149, 2009). "For example, lupus prone mice, depleted of CD4+CD25+ cells by thymectomy, have enhanced expansion of autoreactive T cells and accelerated autoantibody production." (PMID 19543397, 2009).